RNF168 (ring finger protein 168)
Description:
E3 ubiquitin-protein ligase required for accumulation of repair proteins to sites of DNA damage. Acts with UBE2N/UBC13 to amplify the RNF8-dependent histone ubiquitination. Recruited to sites of DNA damage at double-strand breaks (DSBs) by binding to ubiquitinated histone H2A and H2AX and amplifies the RNF8-dependent H2A ubiquitination, promoting the formation of 'Lys-63'-linked ubiquitin conjugates. This leads to concentrate ubiquitinated histones H2A and H2AX at DNA lesions to the threshold required for recruitment of TP53BP1 and BRCA1. Also recruited at DNA interstrand cross-links (ICLs) sites and promotes accumulation of 'Lys-63'-linked ubiquitination of histones H2A and H2AX, leading to recruitment of FAAP20/C1orf86 and Fanconi anemia (FA) complex, followed by interstrand cross-link repair. H2A ubiquitination also mediates the ATM-dependent transcriptional silencing at regions flanking DSBs in cis, a mechanism to avoid collision between transcription and repair intermediates. Also involved in class switch recombination in immune system, via its role in regulation of DSBs repair. Following DNA damage, promotes the ubiquitination and degradation of JMJD2A/KDM4A in collaboration with RNF8, leading to unmask H4K20me2 mark and promote the recruitment of TP53BP1 at DNA damage sites. Not able to initiate 'Lys-63'-linked ubiquitination in vitro; possibly due to partial occlusion of the UBE2N/UBC13-binding region. Catalyzes monoubiquitination of 'Lys-13' and 'Lys-15' of nucleosomal histone H2A (H2AK13Ub and H2AK15Ub, respectively).
Synonyms: hRNF168; FLJ35794; RIDL
Tractability: Small molecule: a structure with a bound ligand is known. PROTAC: UniProt records ubiquitination sites on it; ubiquitination databases record sites on it.
Target class: Enzyme; Transferase
Gene: Protein-coding gene on chromosome 3 (196,468,783 to 196,503,768, reverse strand). Ensembl gene ENSG00000163961.
Subcellular location: Nucleus
Subcellular location (Human Protein Atlas): Nucleoplasm; Nuclear bodies
Pathways (Reactome):
DNA Repair: Nonhomologous End-Joining (NHEJ); Processing of DNA double-strand break ends; Recruitment and ATM-mediated phosphorylation of repair and signaling proteins at DNA double strand breaks
Cell Cycle: G2/M DNA damage checkpoint
Metabolism of proteins: SUMOylation of DNA damage response and repair proteins
Gene Ontology:
Molecular function: chromatin binding; histone binding; histone H2AK15 ubiquitin ligase activity; histone ubiquitin ligase activity; K63-linked polyubiquitin modification-dependent protein binding; nucleosome binding; protein binding; ubiquitin binding; ubiquitin protein ligase activity; ubiquitin-protein transferase activity
Biological process: DNA damage response; DNA repair-dependent chromatin remodeling; double-strand break repair; double-strand break repair via classical nonhomologous end joining; double-strand break repair via nonhomologous end joining; epigenetic regulation of gene expression; negative regulation of transcription elongation by RNA polymerase II; positive regulation of DNA repair; protein K63-linked ubiquitination; protein ubiquitination; response to ionizing radiation; ubiquitin-dependent protein catabolic process; interstrand cross-link repair; isotype switching; DNA metabolic process; response to radiation
Cellular component: nuclear body; nucleoplasm; nucleus; protein-containing complex; site of double-strand break; ubiquitin ligase complex; catalytic complex
Genetic constraint (gnomAD): Loss-of-function variants: 37 observed, 34.62 expected, observed/expected ratio (o/e) 1.07, 90% interval 0.82 to 1.41. The upper end of that interval is the gene's LOEUF score, 1.41, which puts it in group 5 of 6, group 1 being the genes least tolerant of losing a copy. Missense variants: 613 observed, 617.66 expected, observed/expected ratio (o/e) 0.99, 90% interval 0.93 to 1.06. Synonymous variants: 226 observed, 232.91 expected, observed/expected ratio (o/e) 0.97, 90% interval 0.87 to 1.08.
Gene-disease validity (ClinGen):
ClinGen rates the evidence that RNF168 causes each of these diseases.
RIDDLE syndrome (autosomal recessive): Definitive. A syndrome of increased radiosensitivity, immunodeficiency, mild motor control and learning difficulties, facial dysmorphism, and short stature.
Homologues: Orthologues: macaque RNF168 (88% identical), chimpanzee RNF168 (80% identical), dog RNF168 (77% identical), rabbit RNF168 (70% identical), rat Rnf168 (64% identical), mouse Rnf168 (64% identical), guinea pig RNF168 (64% identical), tropical clawed frog rnf168 (39% identical), zebrafish rnf168 (28% identical), Caenorhabditis elegans T02C1.2 (6% identical). Paralogues in human: RNF169 (22% identical).
Diseases named in the same sentence as RNF168 in open-access papers:
RNF168 is named in the same sentence as 50 diseases in open-access papers, as found by Europe PMC text mining. Sharing a sentence is not in itself a finding about the gene and the disease. The quoted sentences say what the papers report.
Immunodeficiency (16 papers, 2009 to 2026). Failure of the immune system to protect the body adequately from infection, due to the absence or insufficiency of some component process or substance. "AR deficiencies in RNF168 have been reported in less than 10 patients and are associated with variable immunodeficiency, radiosensitivity, variable neurological abnormalities and dysmorphic features, and some patients present with ATM-like phenotype." (PMID 36986362, 2023). "Germline mutations in the RING finger protein gene RNF168 have been identified in a combined immunodeficiency disorder called RIDDLE syndrome." (PMID 29255463, 2017). "In mice, loss of RNF168 causes immunodeficiency and radiosensitivity as well as increased genomic instability." (PMID 26455503, 2016). "In this study, we show that Rnf168 deficiency in mice leads to increased radiosensitivity, immunodeficiency, and defective spermatogenesis." (PMID 21552324, 2011). "RIDDLE syndrome, caused by mutations of the human RNF168, is a novel hereditary disease clinically characterized by radiosensitivity, immunodeficiency, dysmorphic features, and learning difficulties." (PMID 21552324, 2011). "RNF168 deficiency is presently classified as combined immunodeficiency with syndromic features." (PMID 29255463, 2017). "RNF168 deficiency causes radiosensitivity, immunodeficiency, dysmorphic features, and learning difficulties syndrome and may account for the radiation sensitivity." (PMID 28603521, 2017). "RNF168 is involved in the repair of DNA double-strand breaks, and mutation of this gene is associated with Riddle syndrome, symptoms of which include increased radiosensitivity, immunodeficiency, motor control and learning difficulties, facial dysmorphism, and short stature." (PMID 38990837, 2024). "It is anticipated that, with the increasing use of next-generation sequencing in the diagnosis of immunodeficiency disorders, additional patients with RNF168 mutations might be identified and can help to define and perhaps extend the clinical spectrum of RNF168 deficiency." (PMID 29255463, 2017). "Dysfunction of RNF168 has been closely linked to a variety of human diseases, including breast cancer, esophageal cancer, and RIDDLE syndrome—a rare immunodeficiency and radiation sensitivity disorder associated with defects in DSB repair." (PMID 39996778, 2025). "We confirmed these findings in an siRNA-independent manner by utilizing fibroblasts from an RNF168-deficient RIDDLE patient who suffers from radiosensitivity and immunodeficiency, and displays dysmorphic features." (PMID 28240985, 2017). "Mutations in RNF168 result in RIDDLE (radiosensitivity, immunodeficiency, dysmorphic features and learning difficulties) syndrome, which manifests with multiple symptoms including immune defects." (PMID 26455503, 2016). "RNF168 is mutated in RIDDLE syndrome, which is characterized by radiosensitivity, immunodeficiency, dysmorphic features and learning difficulties." (PMID 21552324, 2011). "Noteworthy, Durocher and colleagues identified two mutations in RNF168 gene as responsible of the RIDDLE (radiosensitivity, immunodeficiency, dysmorphic features and learning difficulties) syndrome, a recently described immunodeficiency disorder." (PMID 19500350, 2009). "Functionally, bi-allelic heterozygous nonsense mutations in the gene encoding RNF168 cause RIDDLE syndrome (radiosensitivity, immunodeficiency, dysmorphic features and learning difficulties) and depletion of either RNF8 or RNF168 in cells causes hypersensitivity to DSB inducing agents." (PMID 25833379, 2015). "In line with an involvement of the RNF8-RNF168 pathway in hematopoiesis, inactivating mutations in RNF168 are associated with the RIDDLE syndrome, characterized by cellular radiosensitivity and immunodeficiency, features which are recapitulated in knockout mouse models for these E3s." (PMID 26442100, 2015).
Immunodeficiency (continued). "The second patient with RNF168 deficiency has been described in the literature with a somewhat different clinical phenotype including mild gait ataxia, ocular telangiectasia, elevated AFP, immunodeficiency, microcephaly, growth retardation, and terminal respiratory failure." (PMID 29255463, 2017). "Collectively, these data demonstrate that Rnf168 is required for in vitro and in vivo CSR, and its inactivation in mutant mice leads to immunodeficiency, which parallels the symptoms of the RIDDLE syndrome." (PMID 21552324, 2011). "It is of interest that another E3 ligase, RNF168, which acts together with UBC13 to amplify the RNF8-dependent histone ubiquitylation has been shown to be defected in RIDDLE syndrome, which is an immunodeficiency and radiosensitivity disorder." (PMID 21774837, 2011).
RIDDLE syndrome (16 papers, 2010 to 2025). "A mouse model of Riddle syndrome found RNF168 deficiency caused decreased spermatogenesis, and RNF168 was identified as a tumor suppressing candidate gene in testicular embryonal carcinomas." (PMID 38990837, 2024). "A deletion (c.640_644del5) in RNF168, causative for recessive RIDDLE syndrome, had high prevalence in majority of the analyzed cohorts, but did not associate with breast cancer." (PMID 28386063, 2017). "In this work, we have identified two siblings with RNF168 deficiency, also termed RIDDLE syndrome, for which only two single cases have been published previously." (PMID 29255463, 2017). "Here we report that RNF168, an E3 ligase mutated in the human RIDDLE syndrome, interacts with TOP2α and mediates its ubiquitylation." (PMID 27558965, 2016). "The E3 ligase RNF168 is essential for the signalling of DNA double strand break and its mutations are associated with the RIDDLE syndrome." (PMID 27558965, 2016). "The recently identified RIDDLE syndrome (MIM #611943) has been associated with homozygous RNF168 mutations." (PMID 21054854, 2010). "Particularly interesting is the recurrent RNF168 c.640_644del5 mutation, which clearly represents a founder mutation in Finland, but whether it is causative for RIDDLE syndrome remains to be demonstrated." (PMID 28386063, 2017). "Interestingly, mutations of RNF168 have recently been identified as the genetic defects leading to RIDDLE syndrome in humans." (PMID 21552324, 2011). "Mutation of the RNF168 gene is associated with RIDDLE syndrome." (PMID 21552324, 2011). "Studies of mouse models for Rnf168 mutations are required to determine whether they reproduce characteristics of the RIDDLE syndrome and whether, similar to Rnf8, Rnf168 plays a role in cancer." (PMID 21054854, 2010). "In addition, RNF168 mutations have been causally linked to the human RIDDLE syndrome." (PMID 21552324, 2011). "In the present study, we report polyubiquitylation of TOP2α by RNF168, an E3 ligase known for its role in DSB signalling and being mutated in the human RIDDLE syndrome." (PMID 27558965, 2016). "Although Rnf168−/− mice showed a normal IgA levels in serum, they demonstrated impaired CSR for various IgG isotypes, thus reproducing the CSR defect associated with RIDDLE syndrome." (PMID 21552324, 2011). "A siRNA screen using 53BP1 foci formation as the readout revealed an E3 ligase, Ring finger protein 168 (RNF168), as the gene mutated in RIDDLE syndrome." (PMID 21050475, 2010). "The normal number of lymphocytes in Rnf168−/− mice is in accordance with the lack of lymphopenia in the patient with RIDDLE syndrome." (PMID 21552324, 2011).
breast carcinoma (12 papers, 2016 to 2025). "For example, in breast cancer, RNF168 has been demonstrated to promote K48-linked ubiquitination of FOXM1, targeting it for proteasomal degradation, consequently enhancing cancer cell sensitivity to doxorubicin-class chemotherapeutic agents." (PMID 39996778, 2025). "Paradoxically, some studies also showed that RNF168 deletion led to the accumulation of R-loop in breast cancer and ovarian cancer cells with BRCA1/2 mutation, and the accumulation of R-loop leads to DSB, senescence and subsequent cell death." (PMID 36771081, 2023). "Our data also indicate that RNF168 deficiency, including in human breast cancer cell lines, confers resistance to the anti-cancer drug and TOP2 inhibitor etoposide." (PMID 27558965, 2016). "We also performed in vivo ubiquitylation assays and examined the effect of RNF168 deficiency in human breast cancer cell lines on the level of TOP2α ubiquitylation." (PMID 27558965, 2016). "However, the loss of RNF168 in BRCA1/2-mutated breast cancer cells has also been reported to lead to R-loop accumulation, which triggers double-strand breaks, senescence, and eventual cell death." (PMID 39996778, 2025). "Although we fail to detect the direct association between RNF168 and ERɑ, RNF168, which is detected at the ERɑ promoter region, offers a potential mechanism that RNF168 modulates ERɑ signalling via controlling its transcription in breast cancers." (PMID 29974997, 2018). "We found that, similar to loss of RAD18, UBC13 and PALB2, loss of RNF168 resulted in an increase in fork stalling in both BRCA1-deficient U2OS cells (Supplementary S4A) and BRCA1-deficient breast cancer MDA-MB-231 cells." (PMID 38943334, 2024). "RNF168 has been found to be highly expressed in various tumor cells, such as breast cancer and prostate cancer, and is closely related to the proliferation, migration, invasion, poor prognosis, and survival rate." (PMID 36771081, 2023). "High RNF168 expression levels have been observed in breast cancer and esophageal cancer, as well as genetic alterations in human papilloma virus (HPV)-positive head and neck cancer." (PMID 37760968, 2023). "Although ERɑ has been well documented to have a critical role in aetiology and progression of breast cancer, RNF168 emerges to be an important component in regulation ERɑ transcription in ERɑ‐positive cancer cells." (PMID 29974997, 2018). "To approach the function of RNF168 in breast cancer cells in an unbiased way, we carried out the whole transcriptomic‐based RNA sequence by comparison between control and RNF168 depletion in MFC‐7 cells." (PMID 29974997, 2018). "Here, we report that the nuclear E3 ubiquitin ligase RNF168 promotes ERɑ transcription, ERɑ signalling activity and promotes ERɑ‐positive breast cancer cell proliferation." (PMID 29974997, 2018). "In patients with breast cancer, RNF168 expression level is correlated with poor endocrine treatment outcome." (PMID 29974997, 2018). "Here, we report an important role in ERɑ‐positive breast cancer cells for RNF168 protein in supporting cell proliferation by driving the transcription of ERɑ." (PMID 29974997, 2018). "To confirm RNF168 function in ERɑ‐positive breast cancer, we deplete RNF168 expression by two different siRNAs." (PMID 29974997, 2018). "RNF168 is required for ERɑ‐positive breast cancer cell proliferation and facilitate ERɑ signalling activity possibly through promoting transcription of ERɑ." (PMID 29974997, 2018). "IB analysis indicated lower expression levels of RNF168 in the breast cancer cell lines MDA-MB-415 and MCF7 compared with SKBR3, T47D and MDA-MB-231." (PMID 27558965, 2016). "The physiological relevance of the regulation of FOXM1 by RNF168 is further underscored by the significant inverse correlation between FOXM1 and RNF168 in breast cancer patient samples." (PMID 27526106, 2016). "Together, these results suggest that RNF168 can modulate the turnover of FOXM1 in untreated breast cancer cells and in response to epirubicin." (PMID 27526106, 2016).